INS (insulin)
Diseases named in the same sentence as INS in open-access papers (continued):
Sharing a sentence is not in itself a finding about the gene and the disease.
infection (continued). "This is in line with previous studies, which suggest that insulin plays a key role in coordinating an organism’s response to infection, influencing, in particular, the allocation of resources." (PMID 32366957, 2020). "The data set incorporates blood glucose, insulin, carbohydrate, and self-reported events of infections." (PMID 32784178, 2020). "Leptin (which secretion is enhanced in the SCAT upon infection) and insulin (which blood level is increased in infected mice) have been reported to promote WAT browning." (PMID 32409640, 2020). "Together, these data suggest that toxicity, transcriptional changes, and insulin secretion all contributed to β-cell dysfunction during infection." (PMID 32093375, 2020). "Infection incidence brought about a dramatic increase in blood glucose levels, insulin intake, and reduction in carbohydrate consumption." (PMID 32784178, 2020). "In all these infection incidences, the individual blood glucose levels remain elevated for a prolonged period of time despite low carbohydrate consumption and increased insulin injections as compared with the regular or normal days." (PMID 32784178, 2020). "In general, all of these findings confirm that during infection incidence, blood glucose levels are elevated despite injecting higher amounts of insulin and reduced carbohydrate consumption." (PMID 32784178, 2020). "The mean and SD of blood glucose levels, total insulin (bolus), and total carbohydrate were computed and used for comparison of the infection-induced deviations." (PMID 32784178, 2020). "We confirmed infection by demonstrating that viral protein colocalized with insulin-positive SC-β cells by immunostaining." (PMID 32093375, 2020). "In all the infection cases, the weekly analysis demonstrated that blood glucose levels were elevated despite higher insulin injection and reduced carbohydrate consumption." (PMID 32784178, 2020). "The model is expected to detect deviations from the norm because of infection incidences considering elevated blood glucose levels coupled with unusual changes in the insulin-to-carbohydrate ratio." (PMID 32784179, 2020). "While infection with the separate vectors induced both somatostatin- and insulin-expressing cells, infection with Ad-M3-mCherry resulted in the induction of predominantly insulin-expressing cells." (PMID 33111125, 2020). "Here, infected diabetic mice treated with insulin presented higher number of leukocytes in the lungs and higher secretion of IL-12 p70 in the lungs, suggesting a more effective response to Pb18 infection." (PMID 33312173, 2020). "Mean and standard deviation of blood glucose levels, total insulin (bolus), and total carbohydrate during the preinfection week, infection week, and postinfection week." (PMID 32784178, 2020). "Other effects of Adv 36 infection include changes in insulin sensitivity and glucose tolerance status." (PMID 32415247, 2020). "Their insulin treatment significantly improved preoperative phagocytosis activity of neutrophils and decreased the maximal diameter of surgical site infection in both types of mice." (PMID 32993618, 2020). "Viral protein colocalized with insulin protein, indicating successful infection of insulin-positive cells." (PMID 32093375, 2020). "The comparison of infection week insulin injections with preinfection and postinfection weeks revealed that there was a dramatic increase in the amount of insulin intake during the infection period." (PMID 32784178, 2020). "Similar to the weekly analysis, the infection-induced shift of the blood glucose dynamics, that is, higher glucose production and increased insulin resistance, is clearly shown in both the daily and hourly analyses." (PMID 32784178, 2020). "Remarkably, these changes in blood glucose, insulin and resistin levels persisted long after the infection had resolved (up to 20 weeks post-infection)." (PMID 32409640, 2020).
infection (continued). "The therapy relies on antiviral medications for infection control, pain control, and a specific management plan for DM in which premixed insulin and metformin are the main components." (PMID 32328375, 2020). "In cases of infection, peripheral insulin sensitivity decreases, leading to decreased glucose uptake by insulin-dependent tissues such as skeletal muscle, adipose tissue and probably the ovary in order to preserve glucose for the immune system." (PMID 32953874, 2020). "In this study, the results observed in the lungs of mice 45 days after Pb18 infection showed that insulin treatment resulted in diminished phosphorylation of ERK in nondiabetic mice, and p-p38 was unaltered." (PMID 33312173, 2020). "In contrast, the most common precipitating factor in our study is inappropriate insulin therapy (46.64%) due to poor compliance followed by infections (31.39%)." (PMID 32999787, 2020). "It is well known worldwide that the most common precipitating factor for DKA is infection followed by inappropriate insulin therapy." (PMID 32999787, 2020). "For example, infection by Mycobacterium marinum leads to a decrease in lipid and glycogen stores in fruit flies by impairing insulin signaling through reduced AKT activation." (PMID 32457651, 2020). "Whatever these factors and the pattern of infection are, which is either lytic or persistent, CV-B4 E2 can prevent the differentiation of human pancreatic ductal cells into insulin-producing cells." (PMID 31269669, 2019). "Handwashing prior to testing blood glucose levels and administering insulin is recommended to obtain accurate results, avoid contamination of materials, and prevent infection at the injection site." (PMID 30974788, 2019). "Other studies have shown 21%-66% patients missing their insulin dose and 20%-73% patients of DKA having underlying infections." (PMID 31372327, 2019). "While mosquitoes use an RNAi-dependent response during times of starvation, the bloodmeal provides the insulin needed to activate a JAK/STAT-dependent response during infection." (PMID 31921210, 2019). "Most patients with DKA while taking a SGLT2 inhibitor will have a precipitating event, with dehydration, infection, surgery, and changes in insulin dose being commonly reported." (PMID 31488052, 2019). "For example, infection of mice with N. brasiliensis stimulates the recruitment of IL-4 producing eosinophils to adipose tissue that promote insulin sensitivity and tolerance to glucose." (PMID 30298071, 2018). "Fasting blood glucose was lower in HFD-fed mice infected with Ad-Smads2/3/4 than in uninfected HFD-fed mice and Ad-Smads2/3/4 infection enhanced glucose tolerance and insulin sensitivity in HFD-fed mice." (PMID 29700281, 2018). "In parallel, mice infected with Ad-Smads2/3/4 exhibited lower circulating insulin levels under fasting conditions, whereas Ad-Smad7 infection further increased the levels of circulating insulin (left)." (PMID 29700281, 2018). "In samples obtained 45 days after infection and 12 days after insulin treatment, we observed that the diabetic mice exhibited maintained diabetic parameters through incubation of the fungus." (PMID 30426021, 2018). "In humans, fecal transplantation therapy (FMT) has been used with success to treat infection by the antibiotic resistant bacteria, Clostridium difficile or to increase insulin sensitivity of patients." (PMID 30301167, 2018). "Controlling the blood glucose levels in these patients via insulin administration is important to prevent the spread of infection." (PMID 28418347, 2017). "Although most animals showed a transient decline in blood glucose, infection resulted in several fold increases in plasma insulin, glucagon and glucagon-like peptide 1 (GLP-1)." (PMID 28085952, 2017).
infection (continued). "As just one example, our previous studies in Drosophila larvae have shown that AMPs can be activated infection-independent in response to the metabolic status by dFOXO, a transcriptional regulator of the insulin signaling pathway." (PMID 28520752, 2017). "Evaluation of HIV-1 replication following infection of PBMCs from 3 different donors showed that continuous treatment of cells with 50 μg/ml insulin leads to ~50% reduction of HIV-1 replication." (PMID 28388673, 2017). "Antibiotics, Oseltamivir and Insulin were administrated to control infection and lower the blood sugar." (PMID 28774267, 2017). "Most reported patients had T2DM, and potential triggers were infection, trauma, reduced caloric intake, alcohol use, and reduced insulin doses." (PMID 28589154, 2017). "Infection with S. japonicum was found to increase whole-body and hepatic insulin sensitivity in mice." (PMID 28969688, 2017). "We have now further studied what happens in the muscles of wasp-infected larvae, and found that the infection has strong effects on insulin signaling and glycogen storage in this tissue." (PMID 29146985, 2017). "The most common causes were medication or insulin non-compliance (35.8%), ongoing poor control or under-dosing of medication or insulin (28.9%), and infection from various sources (21.7%)." (PMID 28702883, 2017). "The glucose tolerance test, insulin tolerance test, area under the curve (AUC), fasting insulin concentrations and HOMA-IR were used to assess glucose tolerance and insulin sensitivity in the Infection-Chemotherapy model mice." (PMID 28969688, 2017). "The interactions between infection, insulin signaling, feeding behavior and immune responses involve energy and nutrients." (PMID 29146985, 2017). "Recently, an immunometabolic mechanism for disease tolerance to a murine STm infection was found to involve the microbiome and the insulin-signaling pathway." (PMID 28421074, 2017). "After short-term infection, insulin release in infected cells significantly increased 1.6 fold in comparison to non-infected cells at the same glucose concentration." (PMID 27631977, 2016). "Overexpression of SIRT3 by Lv-SIRT3 infection abolished the palmitate-induced inhibition on both insulin signaling and insulin-stimulated NO production, suggesting that SIRT3 overexpression improves insulin resistance induced by palmitate in endothelial cells." (PMID 27000941, 2016). "In order to shed light on the role played by cPLA2 and iPLA2 in insulin secretion after short-term or long-term infection, their respective mRNA were silenced using specific siRNA." (PMID 27631977, 2016). "The insulin release after short-term infection significantly increased 1.5 fold in presence of 16.6 mM glucose concentration in comparison to non-infected cells." (PMID 27631977, 2016). "After long-term infection, insulin release in infected cells significantly decreased by 60% in comparison to non-infected cells." (PMID 27631977, 2016). "When the infection is carried out long-term, insulin secretion is significantly reduced and at the same time extremely high PLA2 activities and expressions were observed." (PMID 27631977, 2016). "After long-term infection, insulin release in presence of 16.6 mM glucose concentration significantly decreased 5.5 fold in comparison to non-infected cells at the same glucose concentration." (PMID 27631977, 2016). "After infection, cells were grown in suboptimal insulin concentrations (0.05 μg ml−1; 8.6 nM) insufficient to support HeLa cell growth and survival." (PMID 27577745, 2016). "After palmitate administration, Adca-TAK1 markedly blunted insulin signalling in both TRAF3-flox and TRAF3-LKO cells, whereas the TRAF3 overexpression-induced impairment of insulin signalling was largely reversed by Addn-TAK1 infection in primary hepatocytes." (PMID 26882989, 2016).
infection (continued). "In contrast, infection of L6 myoblasts with Ad-PIMT enhanced TNF-α mediated inhibition of insulin stimulated IRS1Tyr608 and AktSer473 phosphorylation." (PMID 26468734, 2015). "Under control of the infection by antibiotics and insulin, blood sugar was decreased down to a normal level." (PMID 26463667, 2015). "Because we demonstrated a high association between glucose concentration and biofilm-forming capacity, the effect of insulin treatment on infection or biofilm formation in a diabetic environment is controversial." (PMID 26244880, 2015). "A recent study shows that insulin treatment improved the surgical site infection outcome by S. aureus in diabetic mice, potentially through the enhancement of neutrophil function." (PMID 26244880, 2015). "This study uncovered a sequential event in which HCV regulates several critical insulin signaling molecules during its early infection, which partially contributes to the mechanical elucidation of HCV-associated IR." (PMID 25645159, 2015). "It is clear that further and specifically designed investigations are needed to clarify the relationship between innate and adaptive immune responses, inflammation, STH infections and insulin sensitivity in humans." (PMID 26061042, 2015). "We next examined the insulin content of the gene-transferred livers at days 3 and 9 after infection." (PMID 25397325, 2014). "I.v. insulin administration improved the glycaemic control but was complicated by central line infection episodes." (PMID 24711924, 2014). "We have previously found that combined with transgenic technology, insulin-secreting cells that overexpress IL-10 by in vitro infection of Ad-rIL-10 still have insulin secretion function even at high glucose condition." (PMID 24663217, 2014). "Release of insulin is decreased when there is a scarcity of dietary fuels, during stress (fever and infection)." (PMID 26556194, 2014). "Melioidosis patients who had insulin as part of their diabetic therapy had a lower incidence of severe manifestations during infection (19.0% versus 41.5%, p = 0.104)." (PMID 24762472, 2014). "At 24 hours after infection, insulin-rescued rats demonstrated a 2-fold increase in C4 concentration compared with diabetic rats (P = 0.02)." (PMID 25610878, 2014). "There was a nonsignificant trend towards increased numbers of bacteria phagocytized at 24 hours after infection in insulin-rescued rats (P = 0.1)." (PMID 25610878, 2014). "C4-opsonization was increased 15-fold for insulin-rescued rats at 24 hours after infection compared with diabetic rats (P = 0.05)." (PMID 25610878, 2014). "At 24 hours after infection, Western blot analysis showed increased C3-forms for insulin-rescued rats compared with diabetic rats." (PMID 25610878, 2014). "The requirement for energy storage is essentially served by the anabolic actions of insulin, during starvation or infection/inflammation it becomes insulin resistant, along with many other adaptations." (PMID 24485020, 2014). "At 24 hours after infection, C3a concentrations increased to 2-fold which is greater for insulin-rescued rats compared with diabetic rats (P = 0.01)." (PMID 25610878, 2014). "At 24 hours after infection, insulin-rescued rats showed a 2-fold increase in IgG compared with diabetic rats (P = 0.001)." (PMID 25610878, 2014). "The way to maintain glucose levels during starvation, pregnancy and infection/inflammation is through insulin resistance in insulin-dependent tissues." (PMID 24485020, 2014). "At 24 hours after infection, a small but statistically significant increase in C3-fragment opsonization was found for insulin-rescued rats compared with diabetic rats (P = 0.05)." (PMID 25610878, 2014). "Overnight fasting blood glucose and plasma insulin levels were similar between Cre and Gal groups 10 days after infection." (PMID 24358267, 2013). "Fasting blood glucose and plasma insulin levels were similar between Cre and Gal groups 10 days after infection." (PMID 24358267, 2013).
infection (continued). "Compared to our standard 5 day post-infection culture (4TF), we found that two additional weeks of culture (referred to as ‘4TFM’) resulted in a 10-fold increase of INS mRNA expression in spheres." (PMID 24252877, 2013). "Subsequently, we measured levels of insulin secreted from INS-1 cells after infection with adenovirus carrying empty vector, KLF11 WT, or KLF11 A347S by ELISA." (PMID 23589285, 2013). "Based on the pathway and GO results described previously insulin signaling appeared to be affected by the infection." (PMID 23682635, 2013). "It is likely that lowered ADN levels induce insulin resistance resulting in disordered glucose metabolism and subsequent infection." (PMID 23520452, 2013). "On the contrary, cells treated with TNF-α and insulin together showed more than a 50 percent decrease in glucose uptake but infection with IGFBP-3 abolished the TNF-α effect and restored levels of glucose uptake." (PMID 23383064, 2013). "The signal was identified as originating from the liver by imaging of extracted tissues 3 days after infection and by immunohistochemical analysis using anti-insulin antibody." (PMID 23593212, 2013). "Within 5 days after infection, we reproducibly detected INS mRNA induction but at extremely low levels relative to adult human islet controls (0.0035 ± 0.0012% of islet levels)." (PMID 24252877, 2013). "Recently, aggressive insulin-based perioperative glucose control was shown to improve patient outcome, including substantial reductions in infection rates." (PMID 23520452, 2013). "The KEGG insulin pathway showed a statistically significant change due to the infection at all time points, and the GO Biological Process insulin receptor signaling pathway showed a statistically significant change at 24 h post infection." (PMID 23682635, 2013). "After infection, to determine the biosynthesis of insulin and assay the insulin expression at the protein level, the differentiated mMSCs were documented by immunofluorescence analyses." (PMID 22761608, 2012). "PTP1B protein was found down-regulated after 24 hours of infection when cells were treated either with insulin or metformin." (PMID 23133528, 2012). "We demonstrate in this paper that there is a disruption in insulin signaling resulting in neuronal dysfunction upon infection with PbA in mice which is improved with adjunctive lithium therapy in chloroquine treated mice." (PMID 23082110, 2012). "Here we review the role of PKR as an eIF2α kinase, its participation in the regulation of the NF-κB, p38MAPK and insulin pathways, and we focus on its role during infection with the hepatitis C virus (HCV)." (PMID 23202496, 2012). "We have shown that PTP1B protein is reduced 24 hours post-infection in cells treated with insulin and metformin." (PMID 23133528, 2012). "All the cells on the slides were incubated with anti-mouse insulin and then red fluorescence was clearly visualized in the nucleus and cytoplasm after the triple infection." (PMID 22761608, 2012). "To define the mechanism of Gpr27 action, we measured transcript levels of selected regulators of the insulin promoter by RT-QPCR in MIN6 cells after Ad-shGpr27 infection." (PMID 22253604, 2012). "DAF-2 insulin/IGF-1 signalling is one of the most extensively studied pathways regulating host infection outcomes in C. elegans." (PMID 22672310, 2012). "Insulin rapidly stimulated l-arginine transport, an effect abrogated by incubation with inhibitors of phosphatidylinositol-3′-kinase or infection with adenoviruses expressing a dominant negative mutant Akt." (PMID 21871446, 2011). "Infection, trauma, myocardial infarction, surgery are some of the conditions which lead to an increase in insulin requirements and thus to DKA." (PMID 22155468, 2011). "Infection of HAECs with Ad.Akt-DN significantly reduced insulin-stimulated l-arginine transport by approximately 30% without reducing basal transport." (PMID 21871446, 2011).